OR1S1 (olfactory receptor family 1 subfamily S member 1)
Description:
Odorant receptor.
Synonyms: OST034; OR11-232
Gene: Protein-coding gene on chromosome 11 (58,212,720 to 58,216,084, forward strand). Ensembl gene ENSG00000280204.
Subcellular location: Cell membrane
Pathways (Reactome):
Sensory Perception: Expression and translocation of olfactory receptors
Genetic constraint (gnomAD): Loss-of-function variants: 0 observed, 0.68 expected, observed/expected ratio (o/e) 0, 90% interval 0 to 1.8. That is too few expected variants to judge how well the gene tolerates losing a copy. Missense variants: 411 observed, 371.81 expected, observed/expected ratio (o/e) 1.11, 90% interval 1.02 to 1.2. Synonymous variants: 156 observed, 141.98 expected, observed/expected ratio (o/e) 1.1, 90% interval 0.96 to 1.25.
Homologues: Orthologues: chimpanzee OR1S1 (98% identical), macaque OR1S1 (92% identical), mouse Or1s2 (79% identical), rat Or1s2 (77% identical). Paralogues in human: OR1S2 (92% identical), OR7C2 (55% identical), OR1F1 (54% identical), OR1J2 (54% identical), OR1J4 (54% identical), OR1N1 (53% identical), OR1N2 (53% identical), OR7C1 (53% identical), OR1G1 (53% identical), OR1M1 (53% identical), OR7D4 (53% identical), OR1I1 (52% identical), and 116 more.